GLI1 (GLI family zinc finger 1)
Diseases named in the same sentence as GLI1 in open-access papers (continued):
Sharing a sentence is not in itself a finding about the gene and the disease.
neuroblastoma (22 papers, 2009 to 2025). Neuroblastoma (NB) is the most common solid, extracranial childhood tumor. "MATN2 and glial differentiation marker PMP22 are among the upregulated genes induced by GLI family zinc finger 1 (GLI1) in SH-SY5Y neuroblastoma cells." (PMID 41189817, 2025). "The mTOR/S6K1-GLI1 crosstalk appears to be context dependent, because in neuroblastoma cells S6K1 and GLI1 have been shown to exert proliferative effects through independent mechanisms and S6K1 does not affect GLI1." (PMID 30934935, 2019). "Although knockdown of either S6K1 or GLI1 reduces the cellular proliferation of neuroblastoma cells, there is little effect of S6K1 on the expression of GLI1 mRNA and protein and on the capacity of GLI1 to activate target genes." (PMID 25134527, 2014). "To investigate the role of S6K1 and GLI1 in neuroblastoma cellular proliferation, we first transfected SK-N-AS cells with siRNAs targeting S6K1 or GLI1." (PMID 25134527, 2014). "GLI2, GLI3 and especially GLI1 knockdown reduced neuroblastoma cell growth compared with siRNA control." (PMID 25134527, 2014). "Our data provide little support for a role of GLI1 signaling as a mediator of the S6K1 proliferative effects in neuroblastoma cells." (PMID 25134527, 2014). "Constitutively active PI3K subunit, p110α, inhibited Gli1 transcriptional activity in neuroblastoma cells, whereas, overexpression of an inactive form of PI3K subunit, p85, enhanced its activity." (PMID 23900341, 2013). "AKT2-mediated inhibition of Gli1 transcriptional activity suppressed the induction of Gli1 target genes involved in the differentiation of neuroblastoma cells." (PMID 23900341, 2013). "Here, we report a PI3K/AKT2-dependent negative regulation of Gli1 transcriptional activity by AKT2 in neuroblastoma cells." (PMID 23900341, 2013). "By modulating the expression of specific genes in the PI3K signaling, we found that PI3K inhibits Gli1 transcriptional activity in neuroblastoma cells." (PMID 23900341, 2013). "Surprisingly, the AKT2 isoform negatively regulated Gli1 function in both neuroblastoma cell lines we tested." (PMID 23900341, 2013). "Taken together, our data confirms that AKT2 inhibits the tumor-suppressive role of Gli1 by suppressing its transcriptional activity in neuroblastoma cells." (PMID 23900341, 2013). "Collectively, our data suggest an inhibitory role for the PI3K/AKT2 signaling on Gli1 transcriptional activity in neuroblastoma cells." (PMID 23900341, 2013). "We also demonstrated that AKT2 overexpression regulates the nuclear-cytoplasmic distribution of exogenous Gli1 protein in neuroblastoma cells by relieving a GSK3β-mediated destabilization of SUFU, a negative regulator of Gli1 nuclear translocation." (PMID 23900341, 2013). "Expression of Gli1, a downstream effector of Hh, correlates with a favorable prognosis in patients with neuroblastoma." (PMID 23900341, 2013). "We also show a novel evidence that AKT2 negatively regulates Gli1 nuclear accumulation, thereby, affecting its function as a transcription modulator in neuroblastoma cells." (PMID 23900341, 2013). "In this respect, neuroblastoma differs from these cancers as Gli1 expression correlates with a more favorable prognosis in patients and induces differentiation of neuroblastoma cells." (PMID 23900341, 2013). "Studies regarding Gli1 in neuroblastoma are limited to immunohistochemical analysis of patient samples and preliminary in vitro experiments." (PMID 23900341, 2013). "Here, we demonstrate, for the first time, that Gli1 transcriptional activity is negatively regulated by PI3K pathway in neuroblastoma." (PMID 23900341, 2013). "Our findings identify a potential novel role for AKT2 in the cytoplasmic retention of Gli1 in neuroblastoma cells." (PMID 23900341, 2013). "Interfering with GLI1/2 expression inhibits TGF-β1-induced EMT in neuroblastoma cells." (PMID 38498906, 2024).
neuroblastoma (continued). "However, as expected, vismodegib combined with topotecan strongly decreased GLi1 expression and these results were consistent in all neuroblastoma cell lines." (PMID 26934655, 2016). "In addition, our data showed HIF-1α, SHH and GLI1 expression levels were related to International Neuroblastoma Staging System (INSS) stages (Spearman rho = 0.415, P < 0.0001; Spearman rho = 0.487, P < 0.0001; Spearman rho = 0.347, P = 0.003)." (PMID 25811359, 2015). "However, as shown in neuroblastoma, Gli1 activity is suppressed by AKT2 which phosphorylates GSK3β, leading to GSK3β stabilizing the inhibitory SUFU/GLI1 complex." (PMID 26512695, 2015). "This suggests that GLI1 inhibition of HH signaling is an effective way to target high-risk neuroblastoma without MYCN amplification and should be considered as an option for neuroblastoma treatment." (PMID 25134527, 2014). "Thus, we conclude that S6K1 and GLI1 signaling exert proliferative effects on neuroblastoma cells through independent mechanisms." (PMID 25134527, 2014). "In this study, we examined the possible interplay of S6K1 and GLI1 signaling in neuroblastoma." (PMID 25134527, 2014). "Hence, we targeted GLI1 using siRNA and examined the proliferative capacity of multiple human neuroblastoma cells lines." (PMID 23900341, 2013). "Moreover, Gli1 overexpression has been shown to decrease the mitotic index of MYCN-amplified neuroblastoma cells." (PMID 23900341, 2013). "Targeting AKT2 signaling and/or activating Gli1 signaling may represent a new therapeutic strategy against undifferentiated neuroblastoma that is often refractory to current treatment regimen." (PMID 23900341, 2013). "Moreover, Gli1 overexpression reduces the mitotic index of neuroblastoma cells, suggesting a tumor-suppressive role of Gli1." (PMID 23900341, 2013). "GLI1 is another promising biomarker, particularly for predicting neuroblastoma (NB) severity with high MYCN expression." (PMID 39568072, 2024). "Crosstalk between PI3K/AKT signaling and Gli1 transcriptional activity and thereby, induction of Gli1 downstream targets, may act as a critical determinant in favor of or against Gli1-mediated cellular differentiation in neuroblastoma." (PMID 23900341, 2013). "Much is unknown about how Gli1 signaling is regulated in neuroblastoma." (PMID 23900341, 2013). "However, the exact cellular mechanism by which Gli1 exerts its anti-tumorigenic function in neuroblastoma remains unclear." (PMID 23900341, 2013). "Moreover, Gli1 overexpression reduces mitotic index and induces transcription of genes involved in the differentiation of neuroblastoma cells; however, much remains unknown regarding the regulation of Gli1 transcriptional activity." (PMID 23900341, 2013). "Our data provides evidence, for the first time, that overexpression of Gli1 retards proliferation and reduces anchorage-independent growth of MYCN-amplified neuroblastoma cells." (PMID 23900341, 2013). "Here, we sought to examine this apparent negative regulation of Gli1 transcriptional activity by PI3K, an oncogenic signaling pathway critical for neuroblastoma progression." (PMID 23900341, 2013). "Alternatively, the PI3K/AKT pathway promotes tumor cell growth independent of GLI1 activity in neuroblastomas, suggesting that PI3K/AKT either operates in parallel to or downstream of the HH pathway in this context." (PMID 34268113, 2021). "The expression of transcription factor GLi1 of the hedgehog pathway in neuroblastoma cells treated with inhibitors and topotecan alone showed no significant changes." (PMID 26934655, 2016). "Our experimental data demonstrate that in the context of the neuroblastoma cells analyzed S6K1 kinase is not activating Hedgehog signaling through GLI1 phosphorylation." (PMID 25134527, 2014).
neuroblastoma (continued). "It should be also noted that a recent kinome-wide siRNA screen in a non-small cell lung cancer cell line revealed that S6K1 silencing does not alter the expression of GLI1 protein and GLI1 regulated genes, in line with our observations in neuroblastoma." (PMID 25134527, 2014). "Our results demonstrate that the impact of S6K1 kinase on neuroblastoma cells is not mediated through modulation of GLI1 expression/activity." (PMID 25134527, 2014). "This was not surprising as Gli1 overexpression induces differentiation of SH-SY5Y neuroblastoma cells and decreases the rate of mitosis in a number of MYCN-amplified neuroblastoma cell lines in vitro." (PMID 23900341, 2013). "Collectively, our findings suggest an important role of Gli1 as a tumor suppressor in neuroblastoma, and offer a mechanism by which AKT2 regulates the subcellular localization, and in turn, inhibits the tumor-suppressive function of Gli1 in neuroblastoma." (PMID 23900341, 2013). "This confirms the negative role of SUFU in Gli1 transcriptional activity as previously demonstrated and a novel demonstration of the same in neuroblastoma." (PMID 23900341, 2013). "Similar to previous studies, our results indicated that BRAF/MEK/ERK signaling positively regulates Gli1 transcriptional activity in neuroblastoma cells (data not shown)." (PMID 23900341, 2013). "Indeed, studies in neuroblastoma showed that S6K1 fails to modulate GLI1 activity, and, surprisingly, GLI1 acts as tumor suppressor in this context and its tumor-suppressive functions are inhibited by AKT2." (PMID 31244888, 2019). "Furthermore, the chromosome 12q arm contains other – in neuroblastoma not infrequently amplified – genes, among them oncogenes and cell cycle-associated genes (MDM2, CDK4, OS9, and GLI1)." (PMID 25161957, 2014). "Additionally, inhibition of this pathway at the level of GLI1 is more potent than SMO blockade in reducing the cellular proliferation of non-MYCN amplified neuroblastoma cell lines." (PMID 25134527, 2014). "Thus, we conclude that the impact of S6K1 on the proliferation of the neuroblastoma SK-N-AS cells is not mediated through GLI1 signaling." (PMID 25134527, 2014). "The slower growth rate of neuroblastoma cells overexpressing Gli1 may be due to reduced cell proliferation as no appreciable change in apoptosis was observed (data not shown)." (PMID 23900341, 2013). "Interestingly, silencing AKT2, but not the AKT1 isoform, significantly increased Gli1 luciferase activity in both human neuroblastoma cell lines examined, thus demonstrating negative regulation of Gli1 by AKT2." (PMID 23900341, 2013). "Notably, Gli1 did not induce N-MYC expression in neuroblastoma cells, but strongly induced RET, a known mediator of RA effect." (PMID 19834598, 2009). "In contrast, a later study demonstrated that the impact of S6K1 on neuroblastoma cells was not mediated through GLI1, as KD of S6K1 did not decrease the protein level of GLI1 and overexpression of GLI1 could not rescue a reduced proliferation observed upon S6K1 KD." (PMID 33081032, 2020). "GANT-61 is an inhibitor of GLI1 and GLI2, known to reduce autophagy in MYCN non-amplified, but not in MYCN amplified neuroblastoma (NB) cells." (PMID 29581853, 2018). "To determine the functional significance of AKT2-mediated inhibition of Gli1 transcriptional activity in neuroblastoma, we quantified the mRNA levels of RET and MATN2 as downstream targets of Gli1 with or without AKT2 overexpression." (PMID 23900341, 2013).
cervical carcinoma (19 papers, 2013 to 2025). A carcinoma arising from either the exocervical squamous epithelium or the endocervical glandular epithelium. "This HPV genome represents a high-risk type that causes cervical cancer, and GLI1 is expressed in several cervical carcinoma cell lines." (PMID 31770404, 2019). "For instance, Prkci has been shown to contribute to radio-resistance in cervical cancer by activating the Hedgehog/GLI1 pathway, enhancing cancer cell survival under treatment." (PMID 41188443, 2025). "Hh signaling is involved in the development of cervical cancer; the expression of all signaling molecules of this pathway (Shh, PTCH, Smo, Gli-1, Gli-2, and Gli-3) is increased in cervical carcinoma and is very rarely found in normal cervical epithelium." (PMID 39274874, 2024). "A recent study found that GLI1 and E6 stimulate their transcriptional expression reciprocally, resulting in a high level of GLI1 and E6 in cervical cancer stem cells." (PMID 35464958, 2022). "The cooperation between GLI1 and E6 maintains the population and stemness of cervical cancer stem cells." (PMID 35464958, 2022). "In this respect, our findings are at odds with recent studies performed on cervical cancer, where over-expression of key Hh components, in particular, GLI1, correlated with disease stage, tumour grade and lymph node involvement." (PMID 30379908, 2018). "Cervical cancer stem-like cells isolated by side population analysis, displayed retention of E6 and GLI1 expression." (PMID 27678330, 2016). "We found that HPV oncoprotein E6 and GLI1, downstream of Hedgehog signaling pathway act in coordination in cervical cancer cell survival and get overexpressed in cervical cancer stem cells." (PMID 27678330, 2016). "Darinaparsin (ZIO-101, S-dimethylarsino-glutathione) is an organic arsenical and has been noted to effectively inhibit Shh-induced Gli1 expression in cervical cancer cells." (PMID 23773282, 2013). "Moreover, CAR inhibited the HH/GLI signaling pathway by down regulating the expression of SMO, PTCH and GLI1 proteins in cervical carcinoma cells." (PMID 36712982, 2022). "A corresponding reduction in level of GLI1 transcripts was observed in cervical cancer cells." (PMID 27678330, 2016). "Co-inhibition of GLI1 and E6 in cervical cancer cells showed additive anti-cancer effects." (PMID 27678330, 2016). "Finally, we demonstrated that inhibition of SOX18 function, using dominant-negative approach, inhibits to some extent GLI1/GLI2-mediated migration of cervical carcinoma cells in vitro." (PMID 26588701, 2015). "Hh and FOXM1 overexpression have been observed in cervical cancer tissue, wherein Shh, PTCH1 and GLI1 correlated with the pathological grade of the tumors and GLI1 and SMO correlated with the clinical stage of the tumors." (PMID 33680951, 2020). "Second, according to RNA-seq databases, GLI1 is expressed at relatively high levels in normal cervix, the natural target tissue of many HPV types, and in cell lines derived from cervical cancer." (PMID 31770404, 2019). "Semi-quantitative analysis of GLI1, GLI2 and GLI3 in cervical cancer cells demonstrated elevated levels of GLI1 transcripts particularly in HPV16-positive SiHa cells." (PMID 27678330, 2016). "Taking together, both GLI1 and GLI2 significantly inducedSOX18 promoter activity in all three cervical carcinoma cell lines, with the strongest effect observed in HeLa cells." (PMID 26588701, 2015). "In cervical cancer, PRKCI mediates radiosensitivity via the Hedgehog/GLI1 pathway 43, and Garcinone C inhibits the tumorigenic and invasive potential of CRC stem-like cells by targeting the Hedgehog/GLI1 signaling pathway." (PMID 40384864, 2025). "The mRNA expression of key proteins such as PTCH1, SMO, and GLI1 was downregulated significantly, indicating that CAR may prevent cervical cancer by modulating hedgehog signaling powerfully." (PMID 36712982, 2022).
cervical carcinoma (continued). "If this is the case, GLI1 inhibitor rather than SMO inhibitor would be more suitable for the development of cervical cancer therapy." (PMID 35464958, 2022).
multiple myeloma (19 papers, 2017 to 2025). "ADAR1-mediated Alu-dependent RNA editing of glioma-associated oncogene (GLI1), a transcriptional activator of the Hedgehog pathway, promoted immunomodulatory drug resistance in multiple myeloma." (PMID 37612540, 2023). "In relapsed multiple myeloma (MM), glioma-associated oncogene 1 (GLI1) upon ADAR1 editing can promote the activation of the Hedgehog signaling pathway and the self-renewal of stem cells by stabilizing their own transcriptional processes." (PMID 37280687, 2023). "However, it was recently shown that GLI1 editing is associated with multiple myeloma development, highlighting the context‐specific impact of this GLI1 post‐transcriptional modification in tumor biology and suggesting that additional investigation into this complex phenomenon is required." (PMID 30098229, 2018). "MM cell lines activate the SHh/Gli1 axis through autocrine SHh, promoting the expression of SHH and Gli1, thereby enhancing proliferation and protecting myeloma cells from spontaneous and stress-induced apoptosis." (PMID 40799240, 2025). "In myeloma, excessive ADAR1 activity leads to the R701G mutation through RNA editing of Glioma-associated oncogene 1 (GLI1) transcription, affecting cancer cell proliferation and resistance to anticancer drugs." (PMID 38493171, 2024). "GLI1 transcript editing rates were observed higher in relapsed multiple myeloma and plasma cell leukemia, leading to increased GLI1 activity and consequently to malignant regeneration in multiple myeloma." (PMID 30158435, 2018). "ADAR1 mediated glioma-associated oncogene 1 (GLI1) editing leads to an R/G amino acid change at residue 701, which is significantly higher in relapsed multiple myeloma (MM) than age matched controls." (PMID 30585209, 2018). "Here the authors show that expression of ADAR1 correlates with poor patient outcomes, and that ADAR1-mediated editing of GLI1 is a mechanism relevant in the context of multiple myeloma progression and drug resistance." (PMID 29203771, 2017). "This conforms with the observation that CD138/Syndecan-1(+) multiple myeloma cells express Hedgehog genes and that inhibition of Smoothened decreased multiple myeloma cell viability by downregulating Gli-1 and Patched1." (PMID 28270211, 2017). "In addition, editing of GLI1 by ADAR1 resulted in an increased proportion of drug-resistant cells in myeloma, suggesting that inhibition of GLI1 editing by ADAR1 could improve the sensitivity of myeloma cells to drug therapy." (PMID 37280687, 2023). "In addition, ADAR1 dependent RNA editing of GLI1 led to resistance of myeloma cells to chemotherapeutic drug lenalidomide treatment, suggesting that inhibition of GLI1 editing could enhance the cell sensitivity to drug treatment." (PMID 30585209, 2018). "In this study, the expression changes of PTCH1, GLI1, GLI2, Hes1, and SHH in the multiple myeloma drug-resistant cell line RPMI 8226/R were first detected." (PMID 35813864, 2022). "The results showed that the expression levels of PTCH1, GLI2, Hes1, and SHH in RPMI 8226/R were greatly increased compared with the multiple myeloma drug-sensitive cell line RPMI 8226/S, while the expression level of GLI1 was notably decreased." (PMID 35813864, 2022). "To determine whether knockdown of ADAR1 could effectively reduce GLI1 editing in ADAR1-enriched cells, we lentivirally transduced human H929 myeloma cells, which harbor 4 copies of 1q21, with shRNA targeting ADAR1 (lenti-shADAR1)." (PMID 29203771, 2017). "Because we recently found that STAT3 induces the expression of GLI1 in chronic lymphocytic leukemia (CLL) and multiple myeloma cells, and because the JAK-STAT pathway is constitutively activated in MF, we wondered whether STAT3upregulates GLI1 in MF fibrocytes." (PMID 35595725, 2022).
multiple myeloma (continued). "In multiple myeloma CSCs, it was shown that SMO and Gli1 were highly expressed in comparison to non-CSCs, and activation of HH signaling by HH ligands promoted multiple myeloma CSC's expansion, whereas inhibition of the HH signaling markedly blocked CSC's clonal expansion." (PMID 28356914, 2017). "In multiple myeloma (MM), amplified ADAR1 edits GLI1 (R701G) and stabilizes GLI1 expression by preventing the binding of its negative regulator, suppressor of fused (SUFU)." (PMID 30619092, 2018).